KEAP1 (kelch like ECH associated protein 1)
Diseases named in the same sentence as KEAP1 in open-access papers (continued):
Sharing a sentence is not in itself a finding about the gene and the disease.
cancer (continued). "It was further found that MNNG&HPV activated the P62/KEAP1/NRF2 signaling pathway to increase the transcription of antioxidant genes HO-1 and NQO-1 by upregulating p62 expression, which enhanced the antioxidant ability of cancer cells and further promoted the occurrence and development of tumors." (PMID 33123313, 2020). "The top 15 SGA-FIs connected with CSMD3 and ZFHX4 also form densely connected networks that include well-known cancer drivers, such as KRAS, GATA3, KEAP1, ERBB2 and STK11, suggesting that alteration of CSMD3 and ZFHX4 may perturb some of the same signaling pathways as do these known drivers." (PMID 31276486, 2019). "However, there are various publications signifying that the stimulation of Nrf2/Keap1-signaling pathway is not beneficial in all cancer types and stages." (PMID 31022969, 2019). "Consistent with the KEAP1-overexpressing microarray data, 64 genes involved in various metabolic functions were enriched under the common GO term “small molecule metabolic process” with the significant p value-6.30E-04, highlighting the crucial role of NRF2 in cancer metabolism." (PMID 29050246, 2017). "Additionally, glutaminase inhibition could be more broadly applicable in a variety of cancer types when combined with a small molecule activator of NRF2, which renders KEAP1 wild type cells highly sensitive to glutaminase inhibition." (PMID 28967864, 2017). "Because of the reduced affinity to Nrf2, these mutant Keap1 proteins could not repress Nrf2 activity and, consequently, Nrf2 was constitutively activated in these cancer cells." (PMID 24212776, 2011). "Since we previously showed that KO of NRF2 or KEAP1 did not limit the capacity of 4-OI to promote VSVΔ51 infection in cancer cells, we further investigated whether the inhibition of the antiviral response to the virus by 4-OI was also modulated independently of the NRF2/KEAP1 axis." (PMID 38750019, 2024). "In addition, in some tumor cells, the mRNA precursor of NRF2 can undergo alternative splicing, resulting in loss of the domain interacting with Keap1, so that Keap1 fails to bind to NRF2 normally, leading to NRF2 stabilization and a decrease in ferroptosis in cancer cells." (PMID 37760042, 2023). "Interestingly, unlike other cancers with high NRF2 activity, KEAP1 mutations rarely occur in ESCC." (PMID 33276631, 2020). "However, tumors without Keap1 mutations also exhibited constitutively activated NRF2, which might due to decreased Keap1 expression in these cancers." (PMID 30811526, 2019). "It is noteworthy that the inhibition of glutaminase by CB-839 as well as the addition of oxidants was found to decrease the endogenous glutamate content and to sensitize cancer cells to NEAA withdrawal, even in absence of alterations in the KEAP1/NRF2 pathway." (PMID 32443774, 2020). "In addition, electrophilic modifiers of Keap1 and inhibitors of its interaction with NRF2 could also be novel therapeutic targets Other ROS scavengers, including metal-base antioxidants, can move the redox balance to its original levels and thereby inhibit cancer cell growth." (PMID 32645959, 2020). "Many of these genes, including KEAP1, HNF1A, NFE2L2 and LRRK2, have implied roles in cancer but no strong mechanistic links to date (Discussion)." (PMID 30803482, 2019). "Given the previously noted reduction in macrophage-related gene expression in KEAP1 and/or STK11 mutant patient tumors, these findings suggest that Kynu expression in GEMMs is primarily driven by macrophage infiltration rather than cancer cell-intrinsic expression." (PMID 40427178, 2025). "Moreover, MINERVAΔC failed to interact with Keap1, implying the importance of the C-terminal region of MINERVA for cancer progression through Nrf2 mediated regulation." (PMID 33142954, 2020).
cancer (continued). "Additionally, analysis of datasets from the Cancer Dependency Map (DepMap) portal did not reveal a substantial correlation between KRAS expression and KEAP1 expression, indicating that NRF2 activation, in the context of KRAS mutations, does not occur via the conventional KEAP1-dependent pathway." (PMID 40091835, 2025). "Finally, analyses of the data from Cancer Therapeutics Response Portal43 revealed that KEAP1 mutant NSCLC cells exhibit more resistance to class 2 FINs (RSL3, ML162, and ML210), but not to FIN56, than do KEAP1 WT NSCLC cells." (PMID 35459868, 2022).
tumor (629 papers, 2011 to 2026). "STK11 mutations frequently co-occur with KRAS and KEAP1 alterations, exhibit low PD-L1 expression, an immunosuppressive tumor microenvironment that leads to the development of PD-1/PD-L1 resistance." (PMID 42187558, 2026). "KEAP1 loss was found to exacerbate tumor burden and accelerate progression to high-grade lesions in a conditional KrasLSL−G12D/+/Trp53f/f mouse model, highlighting its role in both tumor initiation and progression." (PMID 41541668, 2026). "Some studies have shown that NRF gain of function resulting from the loss of interaction with Keap1, promotes tumor growth and confers chemoresistance in cancer cells." (PMID 41187427, 2025). "Specifically, the loss of ADAR1 leads to the upregulation of Keap1, which inhibits Nrf2, resulting in the accumulation of reactive oxygen species (ROS), enhanced apoptosis, and impaired tumor cell proliferation." (PMID 40852728, 2025). "It was also shown that tumor-derived mutations in KEAP1 are hypomorphic with respect to NRF2 inhibition, and that DPP3 overexpression in the presence of these mutants enhances NRF2 activation." (PMID 39941813, 2025). "Meanwhile, the KEAP1 mutation alone is reported to be associated with tumours expressing higher PD-L1 levels." (PMID 40650126, 2025). "Mutations in KEAP1 (Kelch-like ECH-associated protein 1) lead to activation of the Nrf2 (nuclear factor erythroid 2-related factor 2) pathway, thereby promoting tumor cell proliferation and survival." (PMID 40083325, 2025). "In this context, KEAP1-driven co-mutations were also found unresponsive to immunotherapy, despite high tumor mutational burden (TMB), with a decreased OS in LUAD patients." (PMID 40563292, 2025). "Mutations in NFE2L2 and KEAP1 are also prevalent, with 84% of redox tumours exhibiting alterations in these genes." (PMID 40849356, 2025). "A key player in this process is the nuclear factor erythroid 2-related factor 2(Nrf2)—Kelch-like ECH-associated protein 1 (Keap1) pathway, which regulates the antioxidant defense mechanisms of tumor cells." (PMID 40285867, 2025). "Many tumor types, including lung, liver, and head and neck carcinomas, harbor mutations in KEAP1 or NRF2 that lead to sustained Nrf2 activity." (PMID 41415550, 2025). "On the other hand, STK11 and KEAP1 mutations are strongly associated with an immunosuppressive tumor microenvironment." (PMID 40427178, 2025). "CP promoted the β-TrCP-dependent degradation of Nrf2 in a glucocorticoid receptor-dependent manner, and when combined with Rapamycin treatment, CP strongly inhibited the growth of Keap1-mutated tumor cells." (PMID 40422216, 2025). "In contrast, the co-occurrence of the STK11 and KEAP1 mutations appear to drive resistance to ICIs, even in tumors with a high tumor mutational burden (TMB), by shaping an immunosuppressive metabolic environment that impairs immune cell activation." (PMID 40710207, 2025). "This suggests that, beyond the well-known STK11/KEAP1, alterations in other tumor suppressors like SMARCA4 (which often co-mutates with KRAS in smokers) and cell cycle regulators (CDKN2A loss) can also diminish the efficacy of KRAS inhibitors." (PMID 40723270, 2025). "Aberrant activation of the KEAP1/NRF2 signaling pathway is closely associated with tumor cell development and chemoresistance." (PMID 40223081, 2025).
tumor (continued). "Among these five samples, whole exome sequencing data revealed that two PDC models, 193_C and 1081_C presented the same missense mutations in NFE2L2 and KEAP1 as found in the paired tumour tissues." (PMID 39707614, 2025). "Our findings reveal that MLN8237 is particularly effective in inhibiting the growth of KEAP1-mutant or -deficient tumor cells." (PMID 38521813, 2024). "Taken together, these findings indicate that KEAP1-259aa encoded by circKEAP1 acted as a tumor suppressor by suppressing vimentin." (PMID 38383479, 2024). "Studies have shown that Keap1 mutations are frequent in lung squamous cell carcinoma, leading to persistent Nrf2 activation, which promotes drug resistance and tumor growth." (PMID 39682234, 2024). "Tumor characteristics according to the redox-state regulating proteins Nrf2 (Nuclear factor erythroid-related factor 2), Keap1 (Kelch-like ECH-associated protein 1) and MnSOD (Manganese superoxide dismutase)." (PMID 39040459, 2024). "A study has demonstrated that KEAP1 mutations result in the suppression of immune cells within the tumor microenvironment." (PMID 39596025, 2024). "These cells were identified in squamous lung carcinomas with KEAP1 mutations using the tumor immune dysfunction and exclusion (TIDE) analysis within the TIMER2.0 database." (PMID 38542481, 2024). "In this work, we show that tumour-intrinsic KEAP1/NRF2 mutations and subsequent pathway activation can be non-invasively imaged by [18F]FSPG PET imaging in a variety of animal models of NSCLC." (PMID 39690148, 2024). "For example, in tumor cells with fumarate hydratase (FH) deficiency, KEAP1 succination is induced by the abnormal accumulation of fumarate (which is weakly electrophilic), which, in turn, stabilizes NRF2 and activates the antioxidant pathway." (PMID 39061847, 2024). "The KEAP1–Nrf2 signaling pathway has been found to be implicated in drug resistance by diminishing the sensitivity of tumor cells to chemotherapeutics." (PMID 39769005, 2024). "In general, the literature regarding mutations in KEAP1 as a tumor suppressor gene appears to be more extensive than that concerning NFE2L2." (PMID 39061847, 2024). "Known as a tumor suppressor, KEAP1 mutation or deficiency leads to the activation of NRF2 and its downstream targets." (PMID 38521813, 2024). "Overall, the infiltration level of almost all immune cells in the tumour samples with KEAP1 mutation was lower than that of the wild-type samples, and most of them were statistically significant." (PMID 38962454, 2024). "While the role of KEAP1 in tumor metabolism regulation is well-established, there remains a need for further investigation into treating KEAP1-mutant or -deficient NSCLC by targeting specific metabolic features." (PMID 38521813, 2024). "The KEAP1/NRF2 pathway is a master regulator of several redox-sensitive genes implicated in the resistance of tumor cells against therapeutic drugs." (PMID 38791966, 2024). "Our analysis was conducted in A549 cell line that is a suitable study model in vitro, as it is a tumour cell line owing to its point mutation in the Keap1 allele, an important regulator of the cell stress response system." (PMID 37640833, 2024). "We assessed an xCT-specific ADC, HM30-tesirine, in mice bearing H460 xenograft tumours harbouring the D236H KEAP1 loss-of-function mutation." (PMID 39690148, 2024). "The inhibitory role of DDW in tumours is through regulating the reactive oxygen species (ROS)-related genes in Kelch-like ECH-associated protein 1 (Keap 1) and Nuclear erythroid 2-related factor 2 (Nrf2) signalling pathways, further controlling ROS production." (PMID 38732643, 2024).
tumor (continued). "The results indicated that the PD-L1-negative, TMB-low, STK11-mutated, and KEAP1-unmutated groups demonstrated greater tumor reduction than the other groups." (PMID 38611005, 2024). "When combined with PARRI to treat NSCLC with Kelch-like ECH-associated protein 1 (KEAP1) mutation, they can also function as an adjuvant for tumor vaccines in anti-tumor therapy." (PMID 38566036, 2024). "Targeting NFE2L2-dependent AIFM2 expression has shown potential in enhancing ferroptosis-mediated tumor suppression, especially in lung cancer cells deficient in KEAP1." (PMID 39534872, 2024). "With this model, we have demonstrated that KP tumor cell lines expressing a Keap1 loss-of-function point mutation (R470C) grow faster in the lung than those expressing WT Keap1, primarily by suppressing CD8 T cell antitumor surveillance." (PMID 38536921, 2024). "Next, we split the macrophage clusters by Keap1 mutational status of the tumor and assessed infiltration and prognostic markers." (PMID 38542481, 2024). "Conversely, mutations in KEAP1 are associated with a reduction in tumor-infiltrating lymphocytes and cytotoxic T cells, correlating with poorer clinical outcomes in immunotherapy." (PMID 39596025, 2024). "These mutations often disrupt the Keap1-Nrf2 interaction, leading to increased Nrf2 activity and the upregulation of genes that promote tumor survival and progression." (PMID 39682234, 2024). "We assessed an xCT-specific ADC, HM30-tesirine, in mice bearing H460 tumours which harbour the D236H KEAP1 loss-of-function mutation." (PMID 38168428, 2023). "Deletions of 9p21.3, 9p24, STK11 and KEAP1 are associated with an immunologically ‘cold’ tumor microenvironment and immunotherapy resistance." (PMID 37875494, 2023). "Loss of Keap1 in these mice resulted in higher tumor burden with a higher proliferation rate that, in turn, was dependent on the conversion of glutamine to glutamate." (PMID 36509429, 2023). "Keap1 mutations affect the inhibitory activity of Keap1 on Nrf2, and Keap1 loss of function enhances the survival of tumor cells." (PMID 37359553, 2023). "As one of the major antioxidant response signaling pathways, the KEAP1/NRF2 system is closely associated with tumor development and chemoresistance." (PMID 36719368, 2023). "KEAP1 is regarded as a tumor-suppressive gene, and research has shown that a KEAP1 loss-of-function mutation promotes tumor growth." (PMID 36909198, 2023). "In vitro and in vivo studies have demonstrated that co-occurring mutations of STK11 and KEAP1 in KRAS-mutant NSCLC promote tumor growth and confer enhanced resistance to radiotherapy." (PMID 37675220, 2023). "When focusing on miR-507, the authors were able to show the beneficial effect of its exogenous application to animals bearing A549 originating tumors (NRF2 overexpressing/KEAP1 mutated), that was demonstrated through inhibition of the tumor growth." (PMID 35268568, 2022). "Keap1 mutations have been found to cause constitutive activation of Nrf2, which results in the loss of tumor suppressor function of Nrf1." (PMID 35216330, 2022). "Strong nuclear and cytoplasmic and nuclear Nrf2 expression was detected in primary tumor tissues harboring Keap1 mutations (part a)." (PMID 35945195, 2022). "In this paper, the current status of PDL-1 expression on tumour cells, the smoking status of patients, tumour mutational burden, gut microbiome and STK11 and KEAP1 mutations in the tumour as predictive biomarkers for PD(L)-1-based immunotherapy are summarized." (PMID 35200543, 2022). "In this study, the heterodimer, between the wild-type KEAP1 and the mutant KEAP1 subunits, is inactive and is unable to repress NRF2 in tumours with KEAP1 mutations." (PMID 35453348, 2022).